CCL5 (C-C motif chemokine ligand 5)
Diseases named in the same sentence as CCL5 in open-access papers (continued):
Sharing a sentence is not in itself a finding about the gene and the disease.
Sepsis (continued). "By immunohistochemistry and immunofluorescence methods, we found that myeloperoxidase expression significantly increased in sepsis on day 1, higher levels of CCL5 occurred at the plasma level as early as 12 h post-sepsis, and CCL5 mRNA levels increased in parallel with those in the muscularis." (PMID 37063880, 2023). "Li M identified a gene signature, containing the hub genes CCL5, and established a model that could be used to diagnose patients with sepsis." (PMID 36199375, 2022). "CCL5 is a chemokine gene clustered on the chromosome 17, which is a potential target for sepsis." (PMID 36199375, 2022). "Studies have shown that the expression of CCL5 is significantly higher in septic patients than in non-sepsis patients and is also strongly associated with the prognosis of sepsis." (PMID 36389695, 2022). "Reduced CCL5 may thus assist in managing the progression of sepsis." (PMID 38313013, 2024). "Regarding neutrophils, the levels of Tnfα, IL-6, IL-1β, CXCL1, CXCL2, CCL5, and CXCL10 increased significantly in response to sepsis sEVs compared with those from the control group and healthy individuals." (PMID 38910259, 2024). "Pro-inflammatory cytokines, including interleukin-1β (IL-1β), CCL4, CCL5, and CXCL10, have emerged as potential biomarkers with significant implications for diagnosing sepsis and assessing the severity of cytokine storms." (PMID 38496165, 2024). "As sepsis is a systemic intravascular infectious disease, during sepsis, the endothelial cells in the cerebrovascular blood vessels also produce various chemokines, such as CCL2, CCL3, CCL5, CXCL1, CXCL2, CX3CL1, and CXCL8." (PMID 38585633, 2024). "Levels of MIP1-β/CCL4, RANTES/CCL5 and IP10/CXCL10 were significantly lower in children with sepsis when compared to children with malaria (p<0.01), but was higher when compared to febrile controls (p<0.01)." (PMID 35811678, 2022). "Children with sepsis had significantly higher levels of IL-1β, IL-12 and IL-17A compared to febrile controls but lower levels of MIP1-β/CCL4, RANTES/CCL5 and IP10/CXCL10 when compared to children with malaria and febrile controls." (PMID 35811678, 2022). "Comparison of molecules between the control and sepsis groups revealed statistically significant differences, except for IFN-α, IL-1RA, IL-1β, IL-2, IL-6, IL-7, IL-15, LIF, GM-CSF, TNF-α, CCL4, CCL5, and CXCL12." (PMID 31583025, 2019). "γδ T lymphocytes present in the lungs of CLP mice were likely to be originated from peripheral lymphoid organs and migrated towards CCL2, CCL3 and CCL5, which were highly produced in response to CLP-induced sepsis." (PMID 26037291, 2015). "MSCs have been shown to suppress production of pro-inflammatory cytokines and chemokines, including MIP-2(CXCL-2), CCL5, TNF, IL-6, and IL-1β, in animal models of lung injury and sepsis." (PMID 24423010, 2014). "The negative interactions for the sepsis group were between CCL5 and CXCL9, CCL5 and IL-5, and IL2R and IL-17A." (PMID 35811678, 2022). "Similar to IL-10-stimulated cells, neutrophils stimulated by LPS or primed by TNF-α in vitro, as well as from the patients with sepsis or NMOSD, also released VEGF, but with a different pattern of chemokines (IL-8, CCL4, CCL5) and cytokines (IL-2, -5, -9, -15, -17, TNF-α) promoting inflammation." (PMID 35757755, 2022). "Importantly, the levels of CCL4, CCL5 and CXCL10 have been reported to be increased in both sepsis and malaria." (PMID 35811678, 2022). "In animal models of polymicrobial sepsis, neonates tend to show lower absolute plasma concentrations of TNF-α, IL-1α/β, IL-12, GM-CSF, CCL5 (RANTES), macrophage inflammatory protein (MIP)-1β and IFN-γ as compared to adults, when challenged with an equally-lethal dose of “cecal slurry”." (PMID 31456998, 2019).
Sepsis (continued). "Aberrant upregulation and activation of pro-inflammatory cytokines and chemokines, including TNF-α, IL-1β, IL-6, IL-8, CCL5, and CXCL8, has been correlated with the progression of chronic inflammatory diseases, such as tumor, sepsis, rheumatoid arthritis, psoriasis, and cytotoxicity." (PMID 29045468, 2017). "In turn, antibodies to the platelet-derived chemokines CCL5 and CXCL4, pharmacological disruption of the CCL5-CXCL4 heteromers or, neutralization of CCR5 diminish lung edema, neutrophil infiltration, and tissue damage in LPS-,acid- and sepsis-induced ALI." (PMID 27583400, 2016). "Finally, we identified a four-gene signature, containing the hub genes LCK, CCL5, ITGAM, and MMP9, and established a model that could be used to diagnose patients with sepsis." (PMID 35184762, 2022). "The results suggested that the expressions of LCK and CCL5 were significantly higher in normal samples than in samples from patients with sepsis, while the expressions of ITGAM and MMP9 were significantly lower in normal samples than in samples from patients with sepsis in the GSE57065 dataset." (PMID 35184762, 2022). "A principal component analysis and a receiver operator characteristic curve analysis, identified seven potential biomarkers; IL-1β, IL-7, IL-12, IL-1RA, RANTES/CCL5, MIP1β/CCL4 and IP10/CXCL10 that could discriminate children with sepsis from clinical malaria and other febrile conditions." (PMID 35811678, 2022). "Additionally, using an ROC curve analysis, the plasma levels of IL-1β, IL-7, IL-12, IL-1RA, RANTES/CCL5, MIP1B/CCL4 and IP10/CXCL10 could help differentiate children with sepsis from both clinical malaria and febrile controls." (PMID 35811678, 2022). "The in vitro neutralization of CCL2, CCL3 and CCL5 by mAbs inhibited γδ T lymphocyte chemotaxis towards the respective chemokines and lung homogenates obtained from CLP mice, suggesting that these chemokines coordinate γδ T cell in vivo migration into the lungs during severe sepsis." (PMID 26037291, 2015). "However, no study has found a relationship between CCL5 and the prognosis of sepsis." (PMID 36650470, 2023).
lung carcinoma (61 papers, 2007 to 2025). "Pearson correlation analysis revealed that KMT5C expression had a negatively associated with CCL5 levels in the lung cancer specimens (GSE30219)." (PMID 40126333, 2025). "Results of our current comprehensive study of cytokines did reveal that the transfection of miR‐1 into three different human lung carcinoma cell lines harboring EGFR mutations significantly decreased the expression of CCL5, CXCL10, IL‐6, IL‐8, and TNF‐α." (PMID 33305905, 2021). "CCL-5 upregulates HOTAIR in lung cancer, causing cisplatin resistance." (PMID 39717771, 2024). "CXCL10 and CCL5 overexpression is associated with the presence of CD8+ T cells in lung cancer." (PMID 37937640, 2023). "It has been demonstrated that EZH2 stimulates the expression of the C-C motif chemokine ligand 5 (CCL5; also known as RANTES), resulting in the recruitment of macrophages and facilitating lung cancer progression." (PMID 40092694, 2025). "High Ccl5 expression is associated with poor prognosis and diminished CD8 effector function in lung cancer patients." (PMID 38622609, 2024). "Ccl5 production in lung cancer cells contributes to the immunosuppressive lung environment, promoting tumor development." (PMID 38622609, 2024). "C–C motif chemokine ligand 5 (CCL5) is a pro-inflammatory chemokine known to be involved in respiratory infection and diseases including lung cancer." (PMID 37239886, 2023). "On the contrary, CCL5, of which expression was elevated by KRAS mutated lung cancer, exhibited antitumor abilities by recruiting T cells to the TME." (PMID 38097680, 2023). "Studies have reported that several chemokines, such as CCL2, CCL5, CCL4, CXCL19, and CXCL12, are associated with the progression, metastasis, and prognosis of lung cancer." (PMID 36118890, 2022). "Knockdown of EZH2 reduced the CCL5 protein secretion and therefore inhibited the macrophage recruitment, finally leading to the decreased invasion and metastasis ability of lung cancer cells." (PMID 31855281, 2020). "In vitro, EZH2 knockdown in lung cancer cells decreased CCL5 expression, resulting in reduced chemotaxis of macrophages." (PMID 32630699, 2020). "Mechanistically, the promotion ability of EZH2 on cell migration and invasion of lung cancer was also inhibited by CCL5 knockdown." (PMID 31855281, 2020). "The in vivo subcutaneous xenotransplanted tumor model also revealed that silence of EZH2 suppressed lung cancer metastasis and macrophages infiltration via regulation of CCL5." (PMID 31855281, 2020). "CCL5 is involved in lung cancer cell (A549 cell line) migration by activating the PI3K/Akt/NF-kB pathway that increases the expression of integrin αvβ3." (PMID 32630699, 2020). "Taken together, EZH2 knockdown in lung cancer cells inhibited chemotaxis of macrophages and decreased CCL5 expression." (PMID 31855281, 2020). "CCL5 stimulation increased phosphorylation of Akt, activated NF-κB signal pathway, promoting human lung cancer migration." (PMID 29088737, 2017). "A previous report demonstrated that the HDACi romidepsin enhances response to PD-1 blockade in lung cancer by inducing the expression of CCL5, CXCL9 and CXCL10, and thus enhancing T cells infiltration." (PMID 29371976, 2017). "It has recently been shown that NF-κB enhances the expression of T cell chemokines CCL2 and CCL5 to increase T cell tumor infiltration and tumor rejection in mouse tumor models and human lung cancer patients." (PMID 27014915, 2016). "In previous study has been reported that CCL5 increased lung cancer migration through PI3K/Akt pathway." (PMID 22506069, 2012). "In addition, we also examined the relationship between KMT5C and CCL5 expression in clinical lung cancer samples." (PMID 40126333, 2025). "The potential mechanism is that SCs-derived CCL5 is responsible for lung cancer EMT." (PMID 40248695, 2025).
lung carcinoma (continued). "It has been found that EZH2 could promote lung cancer metastasis and macrophages infiltration through the up-regulation of CCL5, therefore inhibition of EZH2 could suppress lung cancer progression." (PMID 39065562, 2024). "Notably, Ccl5-expressing CD8 T cells have previously been implicated with a dysfunctional state and poor responses to anti-PD1 therapy in orthotopic lung cancer models." (PMID 38536921, 2024). "In addition, results from ELISA showed that the expression of CCL5 in lung cancer tissues was decreased by EZH2 knockdown." (PMID 31855281, 2020). "CCL5 could increase lung cancer migration 31 and induce macrophage infiltration 32, thus promoting lung cancer progression." (PMID 31855281, 2020). "In conclusion, our findings indicated that EZH2 promoted lung cancer metastasis and macrophages infiltration via upregulation of CCL5, which might be the underlying mechanism of EZH2‐induced lung cancer cell progression." (PMID 31855281, 2020). "Furthermore, it was shown that pretreatment with CCL5 and other cytokines protected lung cancer cells against doxorubicin." (PMID 31955503, 2020). "Moreover, Ccl5 production in lung cancer cells can impact the immune microenvironment." (PMID 38622609, 2024). "Furthermore, CCL5 has been demonstrated as a predictive biomarker for evaluating the migration of tumor cells and induction of macrophage infiltration, thereby contributing to the aggressive progression of lung cancer." (PMID 35982911, 2022). "In addition, CCL5 and IL-6 promote Kras-dependent lung cancer cell proliferation and migration." (PMID 31316109, 2019). "At the same time, CCL5 activates the PI3K/AKT/GSK-3 β/Snail-Twist pathway by binding to CXCR2, contributing to enhanced lung cancer invasiveness and dissemination." (PMID 40248695, 2025). "Our results emphasize that elevated EPI promotes Ccl5 and Cxcl10 recruitment of CD8+ T cells to the tumor site, thereby inhibiting tumor progression in an exercise-induced lung cancer model." (PMID 38622609, 2024). "Then, we explored the role of CCL5 in EZH2‐mediated migration and invasion of lung cancer cells and performed cell wound‐healing and transwell assays." (PMID 31855281, 2020). "Enhanced mRNA and protein levels of CXCL10, CCL5, and IFNβ were observed following silencing of NEAT1 in human and mouse lung cancer cells as measured by qRT-PCR and Western blot analysis, respectively." (PMID 32296457, 2020). "Intriguingly, platelet factor 4 (PF4), an endocrine factor with overexpression correlating with decreased overall survival of patients with lung cancer, emerged as a central node connected with high confidence to SRGN, SPARC, CLU and CCL5." (PMID 31215484, 2019). "It is intriguing that CCL5 and CCR5 were reported to be conversely related with TGFβRII in human lung cancer cells." (PMID 29299159, 2017).
lung carcinoma (continued). "For instance, the SAA1 lung cancer biomarker, neuro-inflammation factor MMP1, the chemokine ligands (C-C motifs) CCL2, CCL5, and CCL20, and cytokines such as IL6, IL8, IL16, were all significantly modulated." (PMID 26950733, 2016). "For example, CAFs secrete CCL5, which elevates HOTAIR expression in lung cancer cells." (PMID 39717771, 2024). "In addition, CCL5 can decreased regulatory T cells (Tregs) through MAPK activation and promote an immune suppressive lung cancer environment." (PMID 37062076, 2023). "The silencing of CCL7, which was downregulated 2-fold due to PARG’s overexpression, was shown to reduce experimental liver metastasis, whereas CCL5 silencing (downregulated 4-fold in our experiments) reduced metastasis of non-metastatic lung carcinoma cells." (PMID 35585513, 2022). "It has been reported that CCL5 acts through PI3K/Akt, which in turn activates IKKα/β and NF-κB, resulting in the activation of αvβ3 integrin and contributing to the migration of human lung cancer cells." (PMID 29844932, 2018). "It has been reported that CCL5 could acts through PI3K/Akt, which in turn activates IKKα/β and NF-κB, and contributing to the migration of human lung cancer cells, and NF-κB activation could promote the expression of MMP9." (PMID 29088737, 2017). "Finally, CCL5 regulates PI3K, Akt, and NF-κB cascades, facilitating lung cancer migration." (PMID 38993553, 2024). "In addition, EZH2 has been shown to enhance the expression of CCL5 to promote recruitment of macrophages and invasion in lung cancer, although the mechanism was not clearly identified." (PMID 36038549, 2022).
diabetes (60 papers, 2005 to 2026). "CCL5 is upregulated in diabetes, contributing to the chronic inflammatory state associated with the disease." (PMID 39807180, 2025). "In addition, type 2 diabetes mellitus has been found to be associated with decreased CCL5 levels in patients with chronic periodontitis." (PMID 38139161, 2023). "Although it is implicated in the pathogenesis of diabetes by promoting immune cell recruitment through activation of C-C chemokine receptors (CCRs), RANTES/CCL5 also shows beneficial effects on β-cells through the activation of the G-protein-coupled receptor 75 (GPR75)." (PMID 35628332, 2022). "Global REDD1 deletion attenuated STZ-diabetes induced renal mRNA expression of proinflammatory genes including Ccl5, Vegfa, and Icam-1." (PMID 39920111, 2025). "Elevated levels of CCL5 have been found in the serum and tissues of diabetic patients, indicating its significant role in mediating diabetes-related inflammation." (PMID 39807180, 2025). "The role of CCL5 in diabetic neuropathy has recently been investigated in an STZ-induced mouse model of diabetes." (PMID 39457105, 2024). "Under the chemotaxis of chemokines (CCL2, CX3CL1, CCL5, etc.), phagocytes such as monocytes and macrophages gather at the site of diabetes complications." (PMID 36755923, 2023). "We found that CCL5 and CXCR2 polymorphisms were associated with increased cancer risk, while the relationships remained significant after adjustments for age, diabetes, hypertension, or endometrial thickening." (PMID 38001676, 2023). "Studies here extend on the prior report by demonstrating that diabetes-induced NF-κB activation and enhanced expression of CCL5 and CCL2 in the retina also require GSK3 activity." (PMID 37392853, 2023). "In patients with type 2 diabetes mellitus and overt nephropathy, the renal biopsies of CCL5 are significantly elevated, especially in tubular cells, and this increase is directly correlated with proteinuria and interstitial cellular infiltration." (PMID 36059966, 2022). "A recent study investigated potential serum biomarkers for diabetes and observed CCL5 among the nine identified serum proteins." (PMID 33207809, 2020). "SHBG and PRSS2 might explain the beneficial association with IHD; testosterone, SHBG, CCL5, CNDP1, F11, LCN2, and THBS4 might explain the association with diabetes, which provides insights for drug development." (PMID 41882153, 2026). "The hub gene identified in our study in the SOY1.5 group, that correlates with albumin, is CCL5 (RANTES) in diabetes-related renal pathophysiology, and serum albumin may play a relevant role." (PMID 39021677, 2024). "The chemokines regulated on activation, normal T-cell expression, and presumably, secreted (RANTES)/CCL5 was also overexpressed in diabetes, contributing to inflammation within glomerular and tubular cells and exhibiting a strong association with DR progression." (PMID 37092467, 2023). "Similarly, the heightened expression of C-C motif chemokine 5 (CCL5, also known as RANTES) is evident in renal biopsy samples from patients with type 2 diabetes mellitus, predominantly observed in renal tubular cells." (PMID 37859992, 2023). "Additionally, CCL5 levels are increased in patients suffering from diabetes complications." (PMID 39457105, 2024). "Additionally, polymorphisms in C-C motif chemokine ligand 2 (CCL2) gene which codes an inflammatory or inducible chemokine and C-C motif chemokine ligand 5 (CCL5) gene which is a target of NF- B activity, have been suggested to alter the risk of post-transplant diabetes mellitus development." (PMID 33810367, 2021). "Exposure of cultured podocytes to AGE, a diabetes-like condition, increased JAK2 activity and induced expression of SAA3 as well as pro-inflammatory mediators including Cxcl5, Ccl2, and Ccl5." (PMID 30763329, 2019).